RAB4A (RAB4A, member RAS oncogene family)
Description:
The small GTPases Rab are key regulators of intracellular membrane trafficking, from the formation of transport vesicles to their fusion with membranes. Rabs cycle between an inactive GDP-bound form and an active GTP-bound form that is able to recruit to membranes different sets of downstream effectors directly responsible for vesicle formation, movement, tethering and fusion. RAB4A is involved in protein transport. Also plays a role in vesicular traffic. Mediates VEGFR2 endosomal trafficking to enhance VEGFR2 signaling. Acts as a regulator of platelet alpha-granule release during activation and aggregation of platelets (By similarity).
Synonyms: RAB4; HRES-1/RAB4; HRES-1; HRES1
Tractability: Small molecule: a structure with a bound ligand is known. Antibody: UniProt places it where antibodies can reach, with high confidence. PROTAC: ubiquitination databases record sites on it; its protein half-life has been measured.
Gene: Protein-coding gene on chromosome 1 (229,271,062 to 229,305,894, forward strand). Ensembl gene ENSG00000168118.
Subcellular location: Membrane; Cytoplasm; Early endosome membrane; Recycling endosome membrane
Pathways (Reactome):
Vesicle-mediated transport: TBC/RABGAPs; Translocation of SLC2A4 (GLUT4) to the plasma membrane
Metabolism: Synthesis of PIPs at the plasma membrane
Metabolism of proteins: RAB geranylgeranylation
Signal Transduction: MET receptor recycling
Gene Ontology:
Molecular function: G protein activity; GDP binding; GTP binding; GTPase activity; protein binding
Biological process: antigen processing and presentation; regulation of endocytosis; vesicle-mediated transport; neurotransmitter receptor transport postsynaptic membrane to endosome; Rab protein signal transduction
Cellular component: cytoplasm; extracellular exosome; perinuclear region of cytoplasm; vesicle; cytoplasmic vesicle membrane; early endosome membrane; insulin-responsive compartment; recycling endosome; recycling endosome membrane; endosome; glutamatergic synapse; membrane
Genetic constraint (gnomAD): Loss-of-function variants: 9 observed, 18.86 expected, observed/expected ratio (o/e) 0.48, 90% interval 0.29 to 0.83. The upper end of that interval is the gene's LOEUF score, 0.83, which puts it in group 3 of 6, group 1 being the genes least tolerant of losing a copy. Missense variants: 166 observed, 189.88 expected, observed/expected ratio (o/e) 0.87, 90% interval 0.77 to 0.99. Synonymous variants: 78 observed, 76.12 expected, observed/expected ratio (o/e) 1.02, 90% interval 0.85 to 1.24.
Homologues: Orthologues: dog RAB4A (99% identical), guinea pig RAB4A (98% identical), rabbit RAB4A (98% identical), mouse Rab4a (98% identical), chimpanzee RAB4A (95% identical), rat Rab4a (94% identical), zebrafish rab4a (94% identical), macaque RAB4A (87% identical), pig RAB4A (83% identical). Paralogues in human: RAB4B (85% identical), RAB14 (58% identical), RAB2B (52% identical), RAB2A (51% identical), RAB11B (44% identical), RAB11A (43% identical), RAB18 (40% identical), RAB43 (40% identical), RAB25 (39% identical), RAB1B (39% identical), RAB1A (38% identical), RAB39A (38% identical), and 56 more.
Diseases named in the same sentence as RAB4A in open-access papers:
RAB4A is named in the same sentence as 23 diseases in open-access papers, as found by Europe PMC text mining. Sharing a sentence is not in itself a finding about the gene and the disease. The quoted sentences say what the papers report.
lupus (14 papers, 2009 to 2025). "To determine its causative involvement in disease pathogenesis, we replaced the wild-type Rab4A alleles in C57Bl/6 (B6) and lupus-prone B6 SLE123 triple congenic (B6.TC) mice with constitutively active Rab4AQ72L alleles surrounded by loxP sites (B6/Rab4AQ72L)." (PMID 38519468, 2024). "Importantly, female B6.TC/Rab4AQ72L lupus-prone mice carrying constitutively active Rab4AQ72L alleles had more severe GN than B6.TC lupus-prone mice with wild-type Rab4A alleles (p = 0.0295)." (PMID 38519468, 2024). "In vivo, constitutively active Rab4A also elevated nicotinamide in lupus-prone mice, which was reversed by pharmacological Rab inhibition, independently linking endosome traffic to NAD+ metabolism." (PMID 40585226, 2025). "The accumulation of mitochondria in CD4+ T cells of B6/Rab4AQ72L and B6.TC/Rab4AQ72L mice is consistent with a role for Rab4A in depleting Drp1 and thus limiting mitophagy in lupus T cells." (PMID 38519468, 2024). "In response to Rab4A-driven lupus pathogenesis, mTORC1 was consistently activated in CD3+, CD4+, and CD8+ T cells of 20-week-old B6.TC/Rab4AQ72L mice relative to B6/Rab4AQ72L controls." (PMID 38519468, 2024). "The overexpression of Rab4A preceded mTOR activation in several spontaneously lupus-prone mouse strains, including B6.TC, NZB/WF1, MRL, lpr, and MRL/lpr mice." (PMID 38519468, 2024). "mTORC1 activation of CD3+, CD4+, and CD8+ T cells of lupus-prone B6.TC/Rab4AQ72L mice was reversed by the inactivation of Rab4A in T cells of B6.TC/Rab4AQ72L-KO mice." (PMID 38519468, 2024). "This study identifies Rab4A-directed endosome traffic as a multilevel regulator of T cell lineage specification during lupus pathogenesis." (PMID 38519468, 2024). "Of note, Rab4A inhibition improves impaired mitophagy of lupus T cells, activation of T cells, and production of autoantibodies in SLE." (PMID 35958572, 2022). "As also shown by this study, Rab4A promotes CD38 recycling and surface expression in CD19+ B cells that likely underlie B cell activation, expansion of plasma cells, and enhanced autoantibody production in lupus-prone B6.TC/Rab4AQ72L mice." (PMID 40585226, 2025). "Rab4A, a small GTPase overexpressed in T cells of patients with systemic lupus erythematosus (SLE), has been shown to activate mechanistic target of rapamycin (mTOR) signaling, which promotes proinflammatory T cell development and predisposes to nephritis in SLE." (PMID 40585226, 2025). "In lupus T-cells, mitochondrial dysfunction including mitochondrial hyperpolarization, mitochondrial accumulation, and impaired mitophagy is mediated by increased Rab4A and its interaction with mTOR." (PMID 39234308, 2024). "Here, we show that constitutive activation of Rab4A in C57Bl/6 (B6) and lupus-prone B6 SLE1.2.3." (PMID 38519468, 2024). "Notably, suppression of Rab-4A ameliorates mitophagy in T-lymphocytes, T-lymphocytes activation, and AAbs genesis in systemic lupus erythematosus." (PMID 39329895, 2024). "Therefore, we created B6/Rab4AQ72L and B6.TC/Rab4AQ72L mice to examine the global impact of Rab4A activation both in B6 control and lupus-prone B6.TC mice." (PMID 38519468, 2024). "Since CD38 expression is upregulated in SLE T cells and correlates with disease activity, our results implicate Rab4A as a potential driver of CD38 dysregulation in lupus." (PMID 40585226, 2025). "The performance of these three methods of extraction was further compared in primary hepatocytes isolated from livers of lupus-prone mice carrying wild-type (B6.TC) or constitutively active Rab4A alleles (B6.TC/Rab4AQ72L) and mice also lacking Rab4A in T cells (B6.TC/Rab4AQ72L-KO)." (PMID 41226410, 2025). "To examine the potential involvement of Rab4A in IL-2 depletion in SLE, we analyzed sera of lupus-prone B6.TC mice." (PMID 40585226, 2025).
lupus (continued). "Here, we identify a functional role for Rab4A-directed endosome traffic in CD98 receptor recycling, mTOR activation, and accumulation of mitochondria that connect metabolic pathways with immune cell lineage development and lupus pathogenesis." (PMID 38519468, 2024). "Importantly, this study identifies Rab4A as a promoter of mTOR activation, ANA production, proteinuria, and GN during lupus pathogenesis in vivo." (PMID 38519468, 2024).
breast carcinoma (4 papers, 2022 to 2024). "In this context, it is worth noting that ACBD3, Arf1, PI4Kβ and Rab4A all have been implicated in breast cancer progression and prognosis and found to be coordinately regulated in the same region of chromosome 1q." (PMID 37048152, 2023). "In a different cell type, BT20 breast cancer cells, knockdown of Rab4a, Rab4b, Rab11a, Rab11b or Rab25 significantly decreased motility, as did knockdown of CLINT1 or SH3BP5L." (PMID 37232246, 2023). "Functionally, RAB4A knockdown essentially abolished breast cancer cell invasion, providing further support for the critical role of RAB4A in supporting EMT." (PMID 36307864, 2022). "To this end, we studied the effect of ITGβ3 overexpression on MCF7 breast cancer cells, which have the characteristics of low RAB4A and ITGβ3 expression, low invasiveness, and predominantly epithelial phenotype." (PMID 36307864, 2022). "For this study, we used MCF7 breast cancer and H1299 non-small cell lung cancer cells that have low intrinsic RAB4A expression and low baseline replating sphere formation ability." (PMID 36307864, 2022). "We also evaluated the expression of ALDH1A3 and CD44, markers for breast cancer stem cells, in both control and RAB4A knockdown cells, and in the RAB4A knockdown cells that concurrently express either RAC1WT or RAC1CA." (PMID 36307864, 2022). "Indeed, TCGA analysis has revealed that increased Rab4A expression predicts poor overall survival of breast cancer patients." (PMID 36307864, 2022). "The impact of RAB4A and RAC1 was also evaluated in the RAB4A-low breast cancer cell line MCF7." (PMID 39463384, 2024). "While The Cancer Genome Atlas (TCGA) database suggests that RAB4A overexpression in breast cancer patients predicts poor overall survival, the functional contribution of RAB4A to tumor development and progression has not been well-evaluated, hence the motivation for this study." (PMID 36307864, 2022).
Autoimmunity (3 papers, 2009 to 2024). The occurrence of an immune reaction against the organism's own cells or tissues. "This suggests that Rab4A-mediated mTOR activation is a driver of autoimmunity via expansion of CD4+ over CD8+ T cells in SLE." (PMID 38519468, 2024). "Interestingly, ANA production was also increased B6/Rab4AQ72L over B6 controls, suggesting that activation of Rab4A alone also triggers autoimmunity on the B6 background." (PMID 38519468, 2024). "Rab4a is known to regulate surface expression of CD4 via endosomal recycling and was shown to cause pro-inflammatory T cell lineage specification and to trigger autoimmunity." (PMID 35603192, 2022). "However, the role of Rab4A-mediated endosome traffic beyond mTOR activation, T-cell lineage development and autoimmunity remain unknown." (PMID 38519468, 2024). "Here the authors characterise how Rab4A is involved with CD98 and endosome recycling which subsequently affects mTOR activation, autoimmunity and T cell expansion." (PMID 38519468, 2024). "While Rab4A activation triggered autoimmunity both in females and males, it failed to influence proteinuria and GN in male B6.TC mice, which may be attributed to gender differences in end-organ resistance in SLE43." (PMID 38519468, 2024).
ovarian carcinoma (3 papers, 2021 to 2024). A malignant neoplasm originating from the surface ovarian epithelium. "This generated a robust catalogue of Rab4a-, Rab11a- and Rab25-associated proteins within migratory A2780 ovarian cancer cells, providing an important resource for further understanding of how trafficking networks perform their myriad functions, including in cell migration." (PMID 37232246, 2023). "Here, we used BioID-based proximity labelling to characterise the protein complexes that form around recycling vesicles in a mesenchymal, migratory, ovarian cancer cell line model, specifically focusing on Rab4a, Rab11a and Rab25." (PMID 37232246, 2023). "Of the three proteins investigated (RAB4A, RAB5A, and RAB11A), only RAB5 expression was found to correlate with T-DM1 toxicity in a cell line panel of HER2-positive breast and ovarian cancer." (PMID 34741021, 2021).
Alzheimer disease (2 papers, 2015 to 2024). A progressive, neurodegenerative disease characterized by loss of function and death of nerve cells in several areas of the brain leading to loss of cognitive function such as memory and language. "Other small GTPases have previously been linked to Alzheimer’s disease, including an involvement of Rab6 in amyloid precursor protein processing, but Rab4a has not been previously implicated." (PMID 25981962, 2015). "This research has identified several genes potentially involved in lipid metabolism in Alzheimer’s disease, including CHAT, RAB4A, ACBD6, and GLA." (PMID 39507054, 2024).
glomerulonephritis (2 papers, 2024 to 2025). A renal disorder characterized by damage in the glomeruli. "Rab4A deletion in T cells and pharmacological mTOR blockade restrain CD98 expression, mitochondrial metabolism and lineage skewing and attenuate glomerulonephritis." (PMID 38519468, 2024).
prostate carcinoma (2 papers, 2015 to 2022). A carcinoma that arises from epithelial cells of the prostate gland. "We then subjected the RAB4A-high PC3 prostate cancer and SNB19 glioblastoma cancer cells to stable RAB4A knockdown, which led to the observation that loss of RAB4A abolished cell invasion in both cell types." (PMID 36307864, 2022). "The expression of RAB4A was significantly decreased in primary prostate cancer when compared to PIN tissue (P ≤ 0.05) and there was a significant reduction of RAB4A expression in metastatic prostate tissue when compared to both non-malignant prostate cancer (P ≤ 0.01) and PIN tissue (P ≤ 0.0001)." (PMID 26473288, 2015).
autoimmune disease (1 paper, 2024). A disorder resulting from loss of function or tissue destruction of an organ or multiple organs, arising from humoral or cellular immune responses of the individual to their own tissue constituents. "The predisposition of B6/Rab4AQ72L mice to MOG-induced EAE indicates that Rab4A activation may broadly enhance CD4+ T cell-dependent autoimmune diseases, including MS106." (PMID 38519468, 2024).
glomerulosclerosis (1 paper, 2024). A hardening of the kidney glomerulus caused by scarring of the blood vessels. "Interestingly, male B6.TC/Rab4AQ72L-KO mice developed severe glomerulosclerosis with greater percentage of glomeruli with sclerosis or hyalinosis relative to B6.TC mice with normal Rab4A alleles." (PMID 38519468, 2024).
lymphopenia (1 paper, 2024). Reduction in the number of lymphocytes. "Thus, the inactivation of Rab4A improved GN1, lymphopenia, and thrombocytopenia, which are commonly found in patients and mice with SLE57." (PMID 38519468, 2024).
melanoma (1 paper, 2020). A malignant, usually aggressive tumor composed of atypical, neoplastic melanocytes. "As reported in the literature, TBC1D16 as a driver of melanoma is a Rab4A GAP that is engaged in the trafficking of transferrin receptor and EGFR." (PMID 33194704, 2020).
Splenomegaly (1 paper, 2024). Abnormal increased size of the spleen. "While total body and heart weights were unaffected, splenomegaly was markedly increased in B6.TC/Rab4AQ72L mice over B6.TC controls at 40 weeks of age, which was completely reversed by the inactivation of Rab4A in T cells of B6.TC/Rab4AQ72L-KO mice." (PMID 38519468, 2024).
triple-negative breast carcinoma (1 paper, 2023). An invasive breast carcinoma which is negative for expression of estrogen receptor (ER), progesterone receptor (PR), and human epidermal growth factor receptor 2 (HER2). "We next sought to confirm our findings using BT20 triple-negative breast cancer cells, which express Rab4a, Rab4b, Rab11a, Rab11b and Rab25." (PMID 37232246, 2023).
infection (7 papers, 2018 to 2025). The state of being infected such as from the introduction of a foreign agent such as serum, vaccine, antigenic substance or organism. "Yersinia pestis targets organelle trafficking and recruits Rab4a early in infection and Rab11b late in infection to prevent phagosome maturation and inhibit acidification in the lumen." (PMID 37841276, 2023). "Knockdown of Rab4a resulted in rapid killing of Y. pestis within 2 h of infection, while changes in bacterial survival in Rab11b siRNA-treated macrophages were not apparent until later." (PMID 29463656, 2018). "To assess the effect of the Rab family on RSV replication, we depleted Rab1a, Rab2a, Rab4a, Rab5a, Rab6a, Rab7a, Rab8a, Rab9a, and Rab11a by treating A549 cells with specific siRNAs (or control siRNA) for 24 h, followed by infection with purified RSV A2 and incubation for another 36 h." (PMID 33504607, 2021). "For instance, EspF recruits clathrin, AP2, early (Rab5a and EEA1) and recycling (Rab4a, Rab11a, Rab11b, FIP2, Myo5b) endocytic proteins to sites of infection." (PMID 31947656, 2020). "We show that type-III secreted components prompt the recruitment of clathrin (clathrin and AP2), early (Rab5a and EEA1) and recycling (Rab4a, Rab11a, Rab11b, FIP2, Myo5b) endocytic machineries to peripheral plasma membrane infection sites." (PMID 31242273, 2019). "As the infection continued, colocalization of the YCV with Rab4a-EGFP decreased, and by 2 and 20 h postinfection, it approached background levels." (PMID 29463656, 2018). "While recruitment of Rab4a was necessary to inhibit YCV acidification and lysosomal fusion early during infection, Rab11b appeared to contribute to later stages of YCV biogenesis." (PMID 29463656, 2018). "Notably, Rab4a, a member of the RAS GTPase superfamily known to regulate membrane trafficking, was a hit in the early infection screen, but not the viability screen." (PMID 40815167, 2025).